ALK (ALK receptor tyrosine kinase)
Diseases named in the same sentence as ALK in open-access papers (continued):
Sharing a sentence is not in itself a finding about the gene and the disease.
non-small cell lung carcinoma (continued). "Anaplastic lymphoma kinase gene (ALK) rearrangement is present in only approximately 5% of non-small cell lung cancers (NSCLCs) and is scarce in LCNEC patients." (PMID 38023218, 2023). "Targeting ALK-fusions in other histologies aside from non-small cell lung cancer has been shown to derive both radiographic response and clinical benefit." (PMID 37041305, 2023). "Subsequently, in 2019, the EMA also approved Lorlatinib for the treatment of certain previously treated patients with advanced ALK-positive non-small cell lung cancer." (PMID 37513921, 2023). "The ALK oncogene is aberrantly expressed in many adult cancers, mainly in non-small-cell lung cancer (NSCLC) and anaplastic large-cell lymphoma (ALCL)." (PMID 36765519, 2023). "Anaplastic lymphoma kinase (ALK)-positive non-small cell lung cancer (NSCLC) has a higher incidence of brain metastasis." (PMID 37038567, 2023). "Despite remarkable initial responses of anaplastic lymphoma kinase (ALK) inhibitors in ALK-positive non-small cell lung cancer (NSCLC) patients, cancers eventually develop resistance within one to two years." (PMID 37036582, 2023). "Drug Alectinib is mainly used for the treatment of non-small cell lung cancer and blocks the activity of ALK." (PMID 37139048, 2023). "Alectinib is a standard initial treatment for patients with advanced anaplastic lymphoma kinase (ALK) rearranged non-small-cell lung cancer (NSCLC)." (PMID 35681698, 2022). "Anaplastic lymphoma kinase (ALK) fusion is found in ~3%–5% of patients with non-small-cell lung cancers (NSCLCs)." (PMID 35301419, 2022). "Anaplastic lymphoma kinase (ALK) gene rearrangements are a rare and unique molecular subset of non-small cell lung cancer (NSCLC), present in approximately 5% of cases overall, most with adenocarcinoma histology." (PMID 36003760, 2022). "Lorlatinib is a third-generation tyrosine kinase inhibitor currently approved for the treatment of anaplastic lymphoma kinase (ALK)-positive metastatic non-small cell lung cancer." (PMID 34698901, 2022). "The association between high cfDNA concentration and poor chemotherapeutic response has also been reported in breast cancer and ALK+ non-small cell lung cancer." (PMID 35884434, 2022). "Anaplastic lymphoma kinase (ALK) fusion gene is an important tumor driver gene of non-small cell lung cancer, accounting for about 5% of patients with non-small cell lung cancer, of which 97% are patients with lung adenocarcinoma." (PMID 36172736, 2022). "In mice bearing wild-type or ALK/ROS1-mutant non-small-cell lung cancer (NSCLC), APG-2449 demonstrates potent antitumor activity, with correlations between pharmacokinetics and pharmacodynamics in vivo." (PMID 35820889, 2022). "In clinic, ALK inhibitors are successfully used to treat non-small cell lung cancer, in which ALK fusion genes were found in approximately 5%." (PMID 35054873, 2022). "The effectiveness of the tyrosine kinase inhibitor ALK (TKI) for non-small cell lung cancer has been confirmed." (PMID 36506539, 2022). "Crizotinib, a class Ia small molecule dual inhibitor of c-MET and anaplastic lymphoma kinase (ALK) had been proposed for advanced non-small cell lung cancer therapy with activation of either c-ros oncogene 1 (ROS-1) or ALK." (PMID 35081970, 2022). "ALK fusion is an important driver mutation that accounts for approximately 3-7% of non-small cell lung cancer (NSCLC) cases, and the most common form is EML4-ALK." (PMID 36275795, 2022). "In non-small cell lung cancer, studies found a chromosomal rearrangement creating a gene fusion product that resulted in a constitutively active ALK protein as the oncologic driver." (PMID 36172151, 2022). "Two patients received MRgRT to 30 Gy in 10 fractions for metastatic ALK-rearranged non-small cell lung cancer and neuroblastoma." (PMID 36713501, 2022).
non-small cell lung carcinoma (continued). "With the identification of gene abnormalities in anaplastic lymphoma kinase (ALK)-positive non-small cell lung cancer (NSCLC), effective ALK tyrosine kinase inhibitors (ALK-TKIs) have been developed for treatment." (PMID 35999557, 2022). "Ganetespib, a heat shock protein 90 inhibitor, used in clinical trials for the treatment of non-small cell lung carcinoma with EGFR, KRAS, or ALK mutations, was effective in all cell lines with a stronger inhibition in CRMM2." (PMID 35326726, 2022). "The EML4(e21)::ALK(e20) fusion with non-canonical breakpoint of EML4 gene at exon 21 has been reported to constitute only about 2% of the ALK-rearrangements in non-small cell lung cancer, where EML4(e6)::ALK(e20) is the most common EML4::ALK variant." (PMID 35237889, 2022). "Two patients received fractionated MRgRT for an ALK-rearranged non-small cell lung cancer and neuroblastoma." (PMID 36713501, 2022). "The first oral ALK TKI approved for the treatment of non-small cell lung cancer (NSCLC) that was positive for ALK, crizotinib, initially showed promising outcomes." (PMID 36499382, 2022). "The following year, Andrew Dhawan and colleagues characterized collateral sensitivities to several tyrosine kinase inhibitors (TKIs) in ALK-positive non-small cell lung cancer (NSCLC)." (PMID 35361803, 2022). "Rearrangements of the anaplastic lymphoma kinase (ALK) gene account for 5-6% in non-small cell lung cancer (NSCLC)." (PMID 36591504, 2022). "Anaplastic lymphoma kinase (ALK)-rearranged non-small cell lung cancer (NSCLC) was first reported in 2007." (PMID 35267492, 2022). "Overall survival from diagnosis of advanced disease of metastatic ALK-positive non-small cell lung cancer patients- cox proportional-hazards model of univariate and multivariate analysis of the full cohort (n = 170)." (PMID 35305096, 2022). "Patients with advanced anaplastic lymphoma kinase (ALK)-rearranged non-small cell lung cancer who are prescribed ALK-tyrosine kinase inhibitors (ALK-TKIs) rarely have complete responses, with residual tumors relapsing as heterogeneous resistant phenotypes." (PMID 35228642, 2022). "Different from EGFR and ALK gene mutations, BRAF V600 mutation is relatively rare in non-small cell lung cancer, about 2–3% of which are adenocarcinoma." (PMID 36380085, 2022). "ROS1 and ALK rearrangements account, respectively, for 2–3% and 3–7% of non-small cell lung cancer cases." (PMID 36142468, 2022). "In this study, the safety, antitumor activity, and pharmacokinetics of WX-0593 were evaluated in advanced non-small cell lung cancer (NSCLC) patients with ALK or ROS1 rearrangement." (PMID 35087031, 2022). "The detection of ROS1 and ALK rearrangements is performed for advanced-stage non-small cell lung cancer." (PMID 36142468, 2022). "Ceritinib is a new anaplastic lymphoma kinase (ALK) inhibitor that has shown greater potency in patients with advanced ALK-rearranged non-small cell lung cancer, including those who had disease progression in crizotinib treatment." (PMID 35727390, 2022). "In conclusion, F-circEA1 can be considered as a proto-oncogene that regulates cell proliferation and apoptosis by affecting the expression of the parental gene EML4-ALK1 and its ALK downstream signaling pathway in non-small cell lung cancer." (PMID 34633654, 2022). "Fusion of the echinoderm microtubule-associated protein 4 (EML4) gene with the anaplastic lymphoma kinase (ALK) gene was first identified in neoplastic non-small-cell lung cancer cells." (PMID 35565331, 2022). "Ensartinib (X-396) is a promising second-generation small-molecule inhibitor of anaplastic lymphoma kinase (ALK) that was developed for the treatment of ALK-positive non-small-cell lung cancer." (PMID 35565470, 2022). "Next-generation sequencing technology has enabled the identification of fusion partners of anaplastic lymphoma kinase (ALK) in non-small cell lung cancer, and various ALK fusion partners have been confirmed." (PMID 35978810, 2022).
non-small cell lung carcinoma (continued). "Alectinib hydrochloride (ALH), an anaplastic lymphoma receptor tyrosine kinase (ALK) inhibitor, is used for the treatment of ALK-positive locally advanced or metastatic non-small-cell lung cancer." (PMID 36015320, 2022). "Crizotinib and alectinib is an ALK-tyrosine kinase inhibitor that has been applied in the treatment of non-small-cell lung cancer." (PMID 35359354, 2022). "For example, asexual lymphoma kinase (ALK) PROTACs have been shown to overcome resistance to ALK inhibitors (such as alectinib, ceritinib, and brigatinib) during the treatment of non-small cell lung cancer." (PMID 35702041, 2022). "The ExoDx Lung (ALK) test measures both circulating tumor DNAs and RNAs to diagnose potential non-small-cell lung cancer patients." (PMID 36568159, 2022). "Anaplastic lymphoma kinase (ALK) alterations in non-small cell lung cancer (NSCLC) can be effectively treated with a variety of ALK-targeted drugs." (PMID 35463328, 2022). "It is an FDA-approved drug for the treatment of patients with metastatic non-small-cell lung cancer (NSCLC) whose tumors are ALK-positive or ROS1-positive." (PMID 35743016, 2022). "Rearrangements involving anaplastic lymphoma kinase (ALK) gene have been reported in ~5% of non-small-cell lung cancer patients." (PMID 35212154, 2022). "Crizotinib has already demonstrated high response rates with minimal toxicity for the treatment of ALK-positive non-small cell lung cancer (NSCLC) and has already been established as standard of care first line therapy in lieu of platinum based chemotherapy." (PMID 35207754, 2022). "Here, we applied cfMeDIP-seq to longitudinally sampled plasma of non-small cell lung cancer (NSCLC) patients with oncogenic rearrangements of the anaplastic lymphoma kinase (ALK) gene." (PMID 36461127, 2022). "PROTAC 44 at approximately 100 nM was able to efficiently degrade both mutant EGFRL858R + T790M and ALK fusion proteins (the two most important targets in non-small-cell lung cancer)." (PMID 35702041, 2022). "An encouraging molecular target for non-small cells lung carcinoma (NSCLC) is the anaplastic lymphoma kinase (ALK)." (PMID 35408636, 2022). "Anaplastic lymphoma kinase (ALK) (ALK)-gene rearrangements ALK+ are oncogenic drivers found in 3–5% of patients with non-small-cell lung cancers (NSCLCs)." (PMID 35406523, 2022). "Anaplastic lymphoma kinase (ALK)-positive non-small-cell lung cancers (NSCLCs) have favorable and impressive response to ALK tyrosine kinase inhibitors (TKIs)." (PMID 35070986, 2022). "Patients with non-small-cell lung cancer, especially those with lung adenocarcinoma, are prone to mutations in a variety of driver genes, including epidermal growth factor receptor (EGFR), anaplastic lymphoma kinase (ALK), and other mutations." (PMID 36304772, 2022). "Targeted therapy has become one of the most important therapeutic innovations for the non-small cell lung cancer category with anaplastic lymphoma kinase (ALK) gene rearrangement." (PMID 34082691, 2022). "Acquired resistance to inhibitors of anaplastic lymphoma kinase (ALK) is a major clinical challenge for ALK fusion-positive non-small-cell lung cancer (NSCLC)." (PMID 35999456, 2022). "Clinical and demographic characteristics of metastatic ALK-positive non-small cell lung cancer patients." (PMID 35305096, 2022). "Here, we used SADDLE to design a set of 60 primers to detect 56 actionable gene fusions for non-small cell lung cancer (NSCLC) across six genes (ALK, ROS1, RET, NRTK1, NTRK2, and NRTK3)." (PMID 35410464, 2022). "In this study, patients with advanced non-small cell lung cancer (NSCLC) with EGFR/ALK wild type (WT) and PDL1 expression ≥ 1%, according to tumor proportion (TPS) score, received the combination of tiragolumab plus atezolizumab vs. atezolizumab alone." (PMID 36077813, 2022). "Our findings suggest that ceritinib can not only suppress ALK-rearranged non-small cell lung cancer but also prevent osteoclastic osteolysis." (PMID 36425467, 2022).
non-small cell lung carcinoma (continued). "Anaplastic lymphoma kinase (ALK) inhibitors have shown significant efficacy in ﻿ALK -rearranged non-small cell lung cancer (NSCLC) patients with good performance status (PS) in multiple randomised studies." (PMID 36072236, 2022). "Further increased YAP nuclear localization has also been reported to be associated with chemotherapy resistance and relapse in EGFR-mutant, KRAS-mutant and B-RRAF mutant, ALK-rearranged non-small-cell lung cancer and RAS-driven neuroblastoma." (PMID 36523977, 2022). "ALK inhibitors (ALKi) are the standard-of-care treatment for metastatic ALK-rearranged non-small cell lung cancer (NSCLC) in the first- and second-line setting." (PMID 35305096, 2022). "ALK inhibitors are the standard-of-care treatment for metastatic ALK-rearranged non-small cell lung cancer in the first- and second-line setting." (PMID 35305096, 2022). "Real-world evidence for brigatinib, a next-generation anaplastic lymphoma kinase-tyrosine kinase inhibitor (ALK-TKI) used in ALK-rearranged non-small cell lung cancer, is scarce." (PMID 35781589, 2022). "EGFR mutation and ALK rearrangement are meaningful targetable driver alterations in lung adenocarcinoma (LUAD) and non-small-cell lung cancer (NSCLC), respectively." (PMID 35596192, 2022). "Consistent with this idea, previous studies have indicated that increased TGFBR2 expression is associated with resistance to ALK and EGFR inhibitors in non-small cell lung carcinoma." (PMID 33837205, 2021). "These tumors have typical molecular and histopathological characteristics of human ALK (+) non-small cell lung cancer with a sensitivity to ALK targeting inhibitors." (PMID 34901007, 2021). "Given mutant ALK has been successfully targeted in other diseases such as in anaplastic large-cell lymphoma, non-small-cell lung cancer and myofibroblastic sarcoma, ALK has been heavily investigated as a therapeutic target in neuroblastoma." (PMID 34064704, 2021). "Crizotinib is the approved treatment for advanced non-small cell lung cancers (NSCLCs) of anaplastic lymphoma kinase (ALK) fusion." (PMID 33761908, 2021). "Recent Phase II studies with only ganetespib, a synthetic HSP90 inhibitor, have yielded a response rate of 50% in non-small cell lung carcinoma patients whose tumors contained ALK translocations." (PMID 34638658, 2021). "We report pre-clinical and clinical studies evaluating novel immunotherapeutic approaches and describe the promises and challenges of incorporating immune-based treatments for ALK-rearranged non-small cell lung cancer." (PMID 33806977, 2021). "ALK-rearranged non-small cell lung cancers are sensitive to ALK-directed tyrosine kinase inhibitors, but generally resistant to single-agent immune checkpoint inhibitors." (PMID 33806977, 2021). "Anaplastic Lymphoma Kinase (ALK) rearrangements have been found in 5–6% of non-small cell lung cancers." (PMID 33806977, 2021). "Crizotinib was approved for metastatic anaplastic lymphoma kinase (ALK)-positive non-small cell lung cancer (NSCLC) in 2011 and metastatic ROS proto-oncogene 1 receptor tyrosine kinase (ROS1)-rearranged NSCLC in 2016." (PMID 34771620, 2021). "Alterations of the anaplastic lymphoma kinase (ALK), most commonly in form of a paracentric inversion resulting in an EML4-ALK fusion transcript, occur in about 4–6% of non-small cell lung cancer (NSCLC)." (PMID 34173019, 2021). "The second-generation ALK inhibitors, such as alectinib, have demonstrated superior efficacy in the ALK+ non-small-cell lung cancer setting." (PMID 34072040, 2021). "Rearrangement of the anaplastic lymphoma kinase (ALK) gene creates potent oncogenic drivers in patients with non-small cell lung cancer (NSCLC) occurring in approximately 3-7% of all cases." (PMID 34660278, 2021).
non-small cell lung carcinoma (continued). "Recent examples include NTRK fusions (e.g., 0.5–4% of colorectal cancer), ROS1 (1–2% of Non-small-cell lung carcinoma), and ALK (~4% of Non-small-cell lung carcinoma), all of which have therapeutics currently in the clinic." (PMID 34504101, 2021). "For example, several studies have shown the reduced efficacy of ICIs in Non-Small Cell Lung cancer patients harboring EGFR mutations and ALK rearrangements." (PMID 33853586, 2021). "Brigatinib is used clinically for the treatment of ALK-positive non small cell lung carcinoma, with reported IC50 of 0.6nM determined by in vitro kinase assay." (PMID 34264955, 2021). "Originally known for its role in the oncogenic fusion gene in anaplastic large cell lymphoma, ALK has been established as a treatment target in various cancers, including subgroups of non-small cell lung cancer and colorectal carcinoma." (PMID 34029351, 2021). "In a pancreatic cancer cell line, we found a fusion between EML4 and ALK, as known from non-small-cell lung cancer." (PMID 33441414, 2021). "The ALK inhibitor crizotinib was developed foremost for non-small cell lung cancer but was quickly utilized in ALK+ ALCL with impressive results." (PMID 34072040, 2021). "Lorlatinib shows promising results in clinical trials with patients suffering from non-small-cell lung cancer with genetic rearrangement of ALK or ROS124,25, however, only a very small percentage of human PDAC patients have detectable ALK expression." (PMID 34099731, 2021). "Another representative example of CDx and enrichment trials is crizotinib, an anaplastic lymphoma kinase (ALK) inhibitor for non-small cell lung cancer (NSCLC) patients." (PMID 34209967, 2021). "Chromosomal inversions involving anaplastic lymphoma kinase (ALK) and echinoderm microtubule associated protein like 4 (EML4) generate a fusion protein EML4-ALK in non-small cell lung cancer (NSCLC)." (PMID 33761896, 2021). "The treatment of anaplastic lymphoma kinase (ALK) rearrangement-positive (ALK-p) advanced non-small cell lung cancer (NSCLC) remains a challenge." (PMID 34359604, 2021). "Opto-dALK was inactive in ALK degradation; however, with UV irradiation, a light- and drug dose-dependent EML-ALK degradation was observed (NCI-H2228 or NCI-3122 non-small cell lung cancer cell lines)." (PMID 34209493, 2021). "Three studies comprising a total of 697 patients with ALK-positive non-small cell lung cancer were included, 380 in the alectinib group and 317 in the crizotinib group." (PMID 34150615, 2021). "The anaplastic lymphoma kinase (ALK) gene translocation is noted in 4–7% of non-small cell lung cancer (NSCLC) cases and results in a fusion between ALK and a second gene (most commonly EML4)." (PMID 35008185, 2021). "Crizotinib was approved by FDA in 2011 and then by EMA for the treatment of ALK-positive, metastatic non-small cell lung cancer (NSCLC)." (PMID 34885651, 2021). "Most of these EML4-ALK-positive non-small cell lung cancer patients respond well to the ALK inhibitor." (PMID 34034462, 2021). "Now, in many different cancers, such as neuroblastoma, and non-small cell lung cancer, rearrangements of ALK are found." (PMID 34530849, 2021). "Anaplastic lymphoma kinase-rearranged non-small-cell lung cancer (ALK+ NSCLC) is a model disease for the use of targeted pharmaceuticals in thoracic oncology." (PMID 33494549, 2021). "Anaplastic lymphoma kinase (ALK) is an important therapeutic target for advanced non-small cell lung cancer (NSCLC)." (PMID 34344501, 2021). "Here, we provide in-depth investigation of copy number alteration (CNA) heterogeneity in phenotypically characterized CTCs at resistance to ALK-TKIs in ALK-positive non-small cell lung cancer." (PMID 34272470, 2021). "Various anaplastic lymphoma kinase inhibitors (ALKIs) have been approved for first-line use in treating anaplastic lymphoma kinase (ALK)-rearranged non-small cell lung cancer (NSCLC)." (PMID 34640394, 2021).